CTTN (cortactin)
Diseases named in the same sentence as CTTN in open-access papers (continued):
Sharing a sentence is not in itself a finding about the gene and the disease.
tumor (continued). "ShGirdin inhibited cell proliferation, induced cell apoptosis and suppressed cell migration and invasion (P<0.001), while overexpression of Cortactin reversed the anti-tumor effect of shGirdin on PANC-1 cells (P<0.05)." (PMID 32369440, 2020). "To assess if the most common gains resulted in increased protein expression of target genes, we assessed Shank2 and cortactin immunoreactivity in normal and tumor esophageal tissues." (PMID 32252688, 2020). "Our results also revealed that upregulation of cholesterol significantly increase membrane fluidity accompanied with Cortactin aggregation, suggesting that lipid metabolism is involved in the formation of invadopodia, and thus promote tumor cell metastasis." (PMID 32033570, 2020). "Cortactin promotes cell motility and tumor metastasis via activation and stabilization of the Arp2/3 complex, which leads to the development of protrusive structures (invadopodia and lamellipodia) and subsequent degradation of the extracellular matrix (ECM)." (PMID 31936446, 2020). "When silencing cortactin and Tks5, the markers of invadopodia formation and functional maturation, the extravasation rate of tumor cells were decreased significantly." (PMID 32793471, 2020). "In our study, we analyzed the role of cortactin and its biological function in the tumor progression of PDAC." (PMID 30976201, 2019). "Cortactin and phosphorylated cortactin (Y421) were investigated immunohistochemically in 66 PDAC tumor specimens." (PMID 30976201, 2019). "In a number of tumor cells, cortactin activation seems to be stimulated by CXCL12, promoting lamellipodia and invadopodia formation." (PMID 30573781, 2019). "To further detect the roles of CD44 and CTTN in RNF128-induced tumor progression, we interfered CD44 or CTTN expression in M14-shRNF128 cells to determine the changes in cellular EMT and stemness." (PMID 30832692, 2019). "Further experiments will be necessary to analyze the functional role of the interaction between cortactin and gelsolin in tumor progression of PDAC." (PMID 30976201, 2019). "Our findings revealed that miR-182 acts as a tumor suppressor molecule in metastasis and invadopodia formation by direct targeting of cortactin in NSCLC." (PMID 29986736, 2018). "CTTN is a cytoskeletal protein whose over-expression increases tumor aggressiveness by promoting tumor migration, invasion, and metastasis." (PMID 30220969, 2018). "Invadopodia adhesion sites in tumor cells are recognized by dot-like aggregates of actin and cortactin, and their membranes penetrate the matrix in the form of filopodia-like extensions assisted by membrane-associated proteolytic enzymes." (PMID 29986736, 2018). "Treatment with ABL kinase inhibitors significantly reduced cortactin tyrosine phosphorylation in invadopodia and consequent actin polymerization, matrix degradation, and 3D tumor cell invasion." (PMID 29774130, 2018). "To link suppressed tumor outgrowth and metastasis to blocked Src signaling pathway, we performed immunohistochemistry to examine the intensity of Tyr421-phosphorylated cortactin and Tyr925-phosphorylated FAK staining on collected tumors." (PMID 30285892, 2018). "GISTIC analysis for amplifications and deletions depicted copy number gain and amplification in ABL2 and CTTN, where the majority of tumor samples had gain or amplification in ABL2." (PMID 29774130, 2018). "This study revealed that mechanistically cyclin G2 is able to recruit cortactin to the leading edge of migrating GBM cells, promoting the subsequent tyrosine phosphorylation of cortactin, which is essential for ruffle formation and tumor cell invasion." (PMID 29165393, 2017). "Overexpression of cortactin, by amplification of the chromosomal band 11q13, increases tumor aggressiveness." (PMID 29152154, 2017). "Over-expression of PTBP1 or cortactin in mRNA levels and protein levels has been proved the relevance of tumor stage and prognosis in CRC previously." (PMID 28404950, 2017).
tumor (continued). "Subsequently, researchers established that CTTN is an F-actin binding protein that stimulates the migration and metastasis of tumor cells." (PMID 27903975, 2017). "We reviewed the state of the art of researches that a Src kinase substrate, cortactin plays an essential role in regulating a myriad of cellular processes, such as actin polymerization, podosome/invadopodia formation, and tumor metastasis." (PMID 29152154, 2017). "Our results demonstrate a unique role for PBF in regulating CTTN function to promote endocrine cell invasion and migration, as well as identify a new targetable interaction to block tumor cell movement." (PMID 27603901, 2016). "The effect of ERK inhibition in invadopodia activity was also observed in cortactin-transfected tumor cells through time-lapse experiments." (PMID 27323814, 2016). "Altogether these results demonstrate that tyrosine phosphorylation is critical to the functional interaction of PBF with CTTN in promoting tumor cell invasion." (PMID 27603901, 2016). "Reductions in cortactin in the tumour cells by siRNA led to a small, but reproducible and significant increase in the level of active integrin, as detected by conformation-specific β1 integrin antibodies." (PMID 27339664, 2016). "Cortactin is recognised for its ability to regulate the submembranous cytoskeleton, and has roles in invadopodia of some tumour cells." (PMID 27339664, 2016). "The over-expression of cortactin in many different types of tumours is accompanied by an increased cell-migration activity and metastatic potential resulting in a worsened prognosis." (PMID 27911942, 2016). "One member of the actin family, frequently overexpressed in multiple human tumours, represents cortactin." (PMID 27911942, 2016). "Asporin promoted the migration and invasion of the tumor cells partially through an EGFR/Src/cortactin- signaling pathway." (PMID 27705916, 2016). "In CRC, irrespective of individual histological differentiation grade, Cortactin is overexpressed compared to normal colorectal epithelium, and immunostaining scores correlate with T and M stage of the tumor." (PMID 26345720, 2015). "Although cortactin inhibition did not sustain in HCT116 cells within 24 h, CBF is still able to block cortactin synthesis in HCT116 tumour tissues of mouse models." (PMID 26134506, 2015). "Apart from the in vitro experiments in 1 % oxygen, the suppression of cortactin was also shown in tissue samples of nude mice bearing HCT116 tumours." (PMID 26134506, 2015). "Subsequently, mice bearing HCT116 tumour were also used to reveal that CBF induced a reduction of cortactin synthesis in tumour tissues." (PMID 26134506, 2015). "In in vitro studies and a mouse tumor model, stable overexpression of Cortactin promoted while downregulation of the protein inhibited SGC-7901 gastric cancer cell migration, invasion, and metastatic spread." (PMID 26345720, 2015). "Flii and cortactin localized together in the tumor cells and islets invading into the dermis (yellow)." (PMID 26497552, 2015). "Cortactin is a tyrosine kinase substrate that plays a central role stabilizing the F-actin filaments at the leading edges of tumor cells and controls protease release at invasion sites." (PMID 25686833, 2015). "The branched actin regulator, cortactin, is a Src kinase substrate and Arp2/3 binding protein that stabilizes the actin filaments at the leading edge of tumor cells." (PMID 25686833, 2015). "Cortactin, a protein known to be involved in cell motility and important in neoplasia development, was also overexpressed in the SWCNT-exposed cells." (PMID 24971065, 2014). "To evaluate the possibility of candidate overexpressed genes as biomarkers for ESCC, we carried out IHC staining with antibody for CTTN on tissue microarrays containing 231 pairs of ESCC tumor tissues and their adjacent normal esophageal epithelia." (PMID 24551190, 2014).
tumor (continued). "The percentage of CTTN overexpression in informative ESCC tumor tissues was up to 63.6% (126/198), which was significantly higher than that in normal esophageal epithelia (26.8%, 53/198, P<0.001, Wilcoxon signed rank test)." (PMID 24551190, 2014). "In vitro, we showed that neutrophils released soluble factors which phosphorylated CORTACTIN in the tumor cells and promoted their migration." (PMID 23423155, 2013). "This interaction is confirmed by our in vitro and in situ studies which show that neutrophils activate (phosphorylate) tumoral CORTACTIN to promote the migration of the tumor cells." (PMID 23423155, 2013). "Due to the ubiquitous presence in cell motility structures, such as lamellipodia and invadopodia, cortactin generates a great deal of interest in the role in tumor invasion." (PMID 23518204, 2013). "To this end, we analyzed CORTACTIN expression in tumor tissues from 89 orohypopharynx carcinoma patients in relation to clinical parameters." (PMID 23423155, 2013). "The evidence supporting such a role is principally derived from cell transplantation studies in which tumor cell invasion correlated with Cortactin expression and invadopodia activity." (PMID 22973180, 2012). "In support of this, EGF-stimulation of tumor cells leads to phosphorylation of cortactin at serine residues 405 and 418 inducing a characteristic shift in cortactin electrophoretic mobility from 80 kDa to 85 kDa." (PMID 21886807, 2011). "Cortactin is simultaneously phosphorylated at S405/418 and Y421 in tumor cells, and through the use of point mutant constructs we determined that serine and tyrosine phosphorylation events lack any co-dependency." (PMID 21079800, 2010). "The localization of pS418 cortactin at regions of HNSCC cellular contact within tumors resembles the localization pattern of pY421 cortactin in this tumor type." (PMID 21079800, 2010). "In solid human tumors, cortactin and cortactin phosphorylated on tyrosine 421 (pY421) localizes to invasive tumor fronts and to cell-cell junctions." (PMID 21079800, 2010). "In this report we have developed phosphorylation-specific antibodies against phosphorylated cortactin S405 and S418 to analyze the subcellular localization of this cortactin form in tumor cells and patient samples by microscopy." (PMID 21079800, 2010). "In HNSCC and several other tumor types, cortactin is present in the cytoplasm and is enriched at cell-cell junctions." (PMID 21079800, 2010). "While these reported discrepancies regarding cortactin function in lamellipodia have yet to be fully reconciled, it is clear that cortactin is an important regulator for normal and tumor cell migration in many cell systems." (PMID 21079800, 2010). "Cortactin phosphorylated at S405/418 is localized to sites of dynamic actin assembly in tumor cells." (PMID 21079800, 2010). "An unambiguous role for cortactin has been shown in invadopodia, where removal of cortactin by RNA interference ablates invadopodia formation in multiple invasive tumor cell types." (PMID 21079800, 2010). "Selumetinib inhibition of cortactin S405/S418 phosphorylation reinforces the MEK-ERK1/2 pathway as the main signaling route responsible for phosphorylating these cortactin sites in tumor cells." (PMID 21079800, 2010). "Cortactin also colocalises with F-actin in invadopodia of metastatic tumour cells, where it participates in degradation of the extracellular matrix around tumours." (PMID 18268492, 2008). "Tumors exhibiting high staining intensity were classified as potentially over-expressing, with 70 out of 258 (27.1%) and 51 out of 295 (17.3%) of tumor samples over-expressing cortactin and FADD, respectively." (PMID 18823530, 2008). "Cortactin overexpression was defined as intense diffuse cytoplasmic and/or plasma membrane staining in >50% of tumour cells." (PMID 18268492, 2008).
tumor (continued). "Accordingly, in several animal models ectopic overexpression of cortactin has been shown to accelerate tumour dissemination, and decreased expression of cortactin, by RNA interference, leads to impaired tumour cell migration and metastasis." (PMID 18268492, 2008). "Cortactin overexpression was significantly associated with higher TNM stage (P=0.005), as 38 out of the 77 cortactin-overexpressing tumours (49%) were stage IV, as compared with 50 out of the total 176 tumours analysed (28%)." (PMID 18268492, 2008). "The association between cortactin expression and tumor differentiation is not fully understood, as previous studies have shown both positive and negative associations." (PMID 40217339, 2025). "Invadopodia formation is characteristic of tumor metastasis, which generally manifests as colocalization of F-actin and Cortactin, and IF revealed that after SPOP was knocked down, the colocalization of Cortactin and F-actin was significantly increased, suggesting an increase in invadopodia." (PMID 41213915, 2025). "CTTN is involved in the invasion and metastasis of tumor cells." (PMID 37970440, 2023). "Finally, we observed a strong correlation between SAMHD1 expression and the activation of FAK and cortactin in tumor tissues obtained from patients with ccRCC." (PMID 37009792, 2023). "Based on these findings, we hypothesized that TRPV4 could likely regulate tumor metastasis through Src-cortactin signaling." (PMID 36499486, 2022). "The binding of FGF7 and FGFR2-IIIb could signal to SRC tyrosine kinase inducing phosphorylation of F-actin binding protein and cortactin, which promote the migration of tumour cells." (PMID 35459137, 2022). "Findings of experimental animal models compared to MCF-7 tumor cells indicated that the mRNA level of CTTN might drive tumor cells to disseminate into lymphatic vessels and develop lymph node metastasis." (PMID 33407452, 2021). "The binding of these proteins further stabilizes the conformation of cortactin and recruits more Arp2/3 complexes, thereby promoting the polymerization of actin in the pseudopod and maintaining the formation and dynamic changes of pseudopods in tumour cells." (PMID 33191645, 2021). "In conclusion, cortactin is a pivoting factor where signal transduction and cytoskeletal organization converge, as it regulates various actin-based cellular processes including cell invasion, cell migration, and tumor cell metastasis." (PMID 31936446, 2020). "The relative abundance of these two cortactin forms seems to relate to tumor tissue." (PMID 31936446, 2020). "Cortactin is increased in Hakai-MDCK tumour xenografts upon Hakin-1 treatment." (PMID 32456234, 2020). "Therefore, this article reviews the correlations between cortactin, the actin cytoskeleton, and the epithelial–mesenchymal transition and discusses its clinical importance in tumor therapy." (PMID 33195233, 2020). "To clarify whether IKKε knockdown affects the invadopodia formation in CRC cells in vivo, we further examined invadopodia formation in the tumor cells in section of primary tumor tissues by staining with invadopodia markers including cortactin and Tks5." (PMID 32104508, 2020). "Cortactin promotes tumor cell invasiveness by forming invadopodia and degrading surrounding ECM." (PMID 33262947, 2020). "However, little is known about the biological function of cortactin and its role in cellular and molecular mechanisms involved in the tumor progression of PDAC." (PMID 30976201, 2019). "Likewise, human neutrophils, after CXCR2-dependent recruitment, and MAPK activation have the ability to induce multiple tumor promoting mechanisms, which includes the cortactin-mediated induction of tumor cell invasion and metastasis in patients." (PMID 31293583, 2019). "Our data provide evidence that upregulation and/or activation of cortactin in a three-dimensional tumor microenvironment might promote migration and invasion in this fatal disease." (PMID 30976201, 2019).
tumor (continued). "Tumor cells growing in a three-dimensional spheroid may develop an acidic microenvironment when compared to two-dimensional tumor models which might contribute to the phosphorylation of cortactin in vitro as well as in the in vivo situation." (PMID 30976201, 2019). "CTTN promotes cell migration, invasion and tumor metastasis in many solid tumors." (PMID 30220969, 2018). "However, hypoxia promoted cortactin relocalization to actin puncta, whose appearance and localization at the ventral side of tumour cells were reminiscent of invadopodia." (PMID 29976963, 2018). "CTTN is another cytoskeletal protein often overexpressed in invasive tumor cells." (PMID 29872504, 2018). "Ultimately, cortactin is a critical mediator of tumor cell invasion." (PMID 29986736, 2018). "Promotion of tumor invasion and metastasis was the role of cortactin over expression in vivo." (PMID 29221118, 2017). "Recently, a report showed that a synergistic reaction exhibited on cortactin and Exo70, which could mediate the secretion of MMPs, and thus regulate tumor invasion." (PMID 29152154, 2017). "Exo70 may be involved in tumor invasion by regulating MMP-9 secretion through synergistic reaction with CTTN in HCC26." (PMID 28698570, 2017). "Knockdown of CTTN in SW1116 suppresses tumor growth in vivo." (PMID 27903975, 2017). "The downregulation of CTTN is responsible for the suppression of tumor growth in vivo." (PMID 27903975, 2017). "We also reviewed the literature that the role of cortactin in tumor invasion." (PMID 29152154, 2017). "In addition, overexpression of cortactin enhances cell migration, invasion, and tumor cell metastasis." (PMID 29152154, 2017). "We therefore investigated whether PTP1B expression has an additional role in suppressing tumor invasion by regulating the phosphorylation of cortactin Y421 at invadopodia." (PMID 27824079, 2016). "Immunoblot revealed that C16 stimulates cortactin phosphorylation in tumor cells." (PMID 27323814, 2016). "As CTTN has a well described role in cell migration and tumor metastasis, we assessed whether the interaction between CTTN and PBF was functional." (PMID 27603901, 2016). "However, since Cortactin is almost ubiquitously expressed, subcellular localization of the protein in tumor cells seems to be critical for its role in cell migration and metastasis." (PMID 26345720, 2015). "Furthermore, while the literature equates the presence of invadopodia with the first steps of the metastatic cascade, in particular intravasation, loss of other invadopodia proteins such as cortactin and MT1-MMP also has an effect on tumor progression." (PMID 25826475, 2015). "Most importantly, CBF could diminish the expression of cortactin in human HCT116 xenograft tumours in nude mouse in vivo." (PMID 26134506, 2015). "Furthermore, univariate analysis was used to evaluate associations between prognosis and several factors including age, sex, tumor cell differentiation, lymph nodes metastasis and CTTN status of ESCC tumors." (PMID 24551190, 2014). "Furthermore, we demonstrated that strong CORTACTIN phosphorylation significantly correlated with strong neutrophilic infiltration in tumor tissues from orohypopharynx carcinoma patients." (PMID 23423155, 2013). "Conversely, cortactin knockdown can decrease tumor cell motility and invasion." (PMID 23518204, 2013). "FER may integrate with the integrin and cadherin complex via phosphorylation of cortactin, a crucial molecule in tumor cell metastasis." (PMID 23420638, 2013). "In addition to the clinical findings, our study provides a biological and mechanistical link between neutrophils and tumoral CORTACTIN by showing that neutrophils phosphorylate CORTACTIN in the tumor cells to promote their migration." (PMID 23423155, 2013). "We initially tested whether neutrophils might upregulate the expression of CORTACTIN in the tumor cells." (PMID 23423155, 2013).